CDC42 (cell division cycle 42)
Diseases named in the same sentence as CDC42 in open-access papers (continued):
Sharing a sentence is not in itself a finding about the gene and the disease.
lung carcinoma (54 papers, 2006 to 2025). "miR-137 inhibits the proliferation of lung cancer cells by targeting Cdc42 and Cdk6, while miR-145 can cause cell cycle arrest at the G0-G1 phase, decrease the S-phase, and inhibit proliferation." (PMID 37958720, 2023). "Overexpression of Cdc42 has been found in several types of cancers including lung cancer and it has been associated with tumor carcinogenesis as well as progression." (PMID 31817718, 2019). "In lung cancer, Rho GTPases, especially RhoA, Rac1, and Cdc42, play key roles in tumor progression and metastasis." (PMID 39870629, 2025). "Mechanistically, lncRNA ROLLCSC can interact with CDC42, a GTPase protein, mediating a positive feedback loop that promotes the entry of more EVs into recipient lung cancer cells (LLC)." (PMID 41716631, 2025). "miR-137 in lung cancer cells significantly downregulates Cdc42 and Cdk6 and induces G1 cell cycle arrest, leading to a significant decrease in cell growth." (PMID 37958720, 2023). "In the current study, we discovered that treating lung cancer cells with cycloartocarpin resulted in a decrease in cellular Cdc42 levels." (PMID 36500213, 2022). "In a recent study, we showed that StarD13 depletion increases invadopodia formation through Cdc42 in normal lung cells and in lung cancer cells." (PMID 34958986, 2022). "ZCL367 has good selectivity to Cdc42 in vitro and inhibits the interaction between Cdc42 and intersectin in lung cancer A549 cell lysates." (PMID 35154449, 2022). "It has also been reported that deletion of p120 can inactivate RhoA but increase the activity of CDC42 and Rac1 and promote the proliferation and invasion of lung cancer cells." (PMID 35251170, 2022). "According to the findings, cycloartocarpin suppressed EMT and FAK/AKT/Cdc42 signaling, which are crucial regulators of migration and metastasis in lung cancer cells." (PMID 36500213, 2022). "In summary, our work uncovered that Hhex negatively regulated cell migration of lung cancer cells by enhancing RHOGDIA interaction with RHOA/CDC42, which reduced downstream effector CF1 phosphorylation, thus inhibiting cell protrusions formation." (PMID 34321041, 2021). "For instance, it promotes lung cancer cell invasion and migration by modulating Rac1/Cdc42 activity." (PMID 33258389, 2021). "For example, GIT1 promotes the migration of lung cancer cells through activating the activity of Rac1/Cdc42." (PMID 34663332, 2021). "For instance, miR-137 is reported to inhibit the proliferation of lung cancer cells by targeting Cdc42 and Cdk6." (PMID 32433716, 2020). "It has been shown that curcumin inhibits metastasis in lung cancer cells by modulating several molecular targets including Cdc42, E-Cadherin, matrix metalloproteinases (MMPs), VEGF, and adiponectin." (PMID 31817718, 2019). "It has been documented that curcumin suppressed migration and invasion of cancer cells by downregulating Cdc42 expression in human cancer cells including lung cancer." (PMID 31817718, 2019). "A study conducted on human lung cancer cells A549 and 801D treated with curcumin demonstrated that curcumin downregulated Cdc-42 expression in a dose-dependent manner." (PMID 31817718, 2019). "Previous studies have demonstrated that curcumin has also inhibited Cdc42 and Rac1 and prevented the migration and invasion of lung cancer." (PMID 29642589, 2018). "Further analyses of clinical specimens uncover a significant positive correlation between CDC42 and type II alveolar epithelial cells marker SP-A, indicating the potential importance of CDC42 in this specific subset of lung cancer." (PMID 28871124, 2017). "EL decreased phosphorylation of FAK and its downstream targets, Src, paxillin, and decreased mRNA expression of cell motility-related genes, RhoA, Rac1, and Cdc42 in lung cancer cells." (PMID 28068967, 2017). "GIT1 expression increased lung cancer cell invasiveness through Rac1/Cdc42 activity and promoted tumor growth and metastasis in vivo." (PMID 26462147, 2015).
lung carcinoma (continued). "Next we examined the Spearman's rho correlation to determine the GIT1 and Rac1/Cdc42 correlation in our lung cancer cohort." (PMID 26462147, 2015). "Our results suggest that GIT1-mediated regulation of lung cancer cell motility depends, at least in part, on its ability to modulate Cdc42 and Rac1 activity." (PMID 26462147, 2015). "The expression level of Cdc42 was found to be up-regulated in many cancers including lung cancer, and Cdc42 induction was shown to enhance cancer migration." (PMID 23874694, 2013). "Cdc42 is overexpressed in many of primary lung cancer patients, and Cdc42 over-expression is significantly associated with high TNM stages and lymph node metastasis and its role has recently been proved in lung cancer." (PMID 23874428, 2013). "We investigated how NO exposure affected the actin organization in lung cancer cells and found that NO upregulates Cdc42 protein and enhances the formation of filopodia in these cells." (PMID 23984323, 2013). "Also, they found downregulation of CDC42 expression upon treatment of human lung carcinoma A549 cells with Rho GTPases inhibitor as atorvastatin." (PMID 37211584, 2023). "Furthermore, inhibitor of CDC42 can suppress cell cycle progression, proliferation, and migration in lung cancer and prostate cancer." (PMID 33946672, 2021). "Recent studies in pancreatic cancer and lung cancer cells showed that ectopically expressed Vav1 acts as an upstream activator of Rac1, RhoA and possibly Cdc42 signaling pathways in response to extracellular stimulation, leading to cytoskeleton changes in cancer cells." (PMID 23342133, 2013). "Thus, the low expression of IFFO1 in lung cancer promoted cell migration and movement, which might be due to an enhancement of N-cadherin, Vimentin, and Cdc42 expression levels." (PMID 40634295, 2025). "Furthermore, similar Cdc42-dependent filopodia formation and cell migration observations were made in other cancer types, including colorectal, ovarian, pancreatic, and lung cancers." (PMID 38612766, 2024). "Generally, these data indicated Hhex could inhibit RHOA and CDC42 activation in lung cancer cells." (PMID 34321041, 2021). "Moreover, H2 administration could significantly alleviate the pathological change of lung cancer tissues from the in vivo mice, as well as cause obvious decreases in CD47 and CDC42 expressions." (PMID 32314789, 2020). "Thus, our clinical data analyses only provide an implication that CDC42 expression might be specifically high in those lung cancer derived from AECII." (PMID 28871124, 2017). "Luteolin repressed cell metastasis in lung cancer via Src/FAK and its downstream Rac1, Cdc42, and RhoA pathways." (PMID 36874921, 2023). "In a recent study, we showed that Cdc42 localizes to TKS4-labeled invadopodia and to the sites of matrix degradation in lung cancer cells." (PMID 34958986, 2022). "In A549 and NCI-H520 lung cancer cells that ectopically express CD47, decreasing Cdc42 levels reduced cancer cell migration and invasion." (PMID 32082311, 2020). "Cdc42 expression level is positively correlated with CD47 expression level in A549 and NCI-H520 lung cancer cell lines." (PMID 32082311, 2020). "Among them, CTNNB1, ZEB1, CDC42, HSP90AA1, BST2, PCNA, and E2F1 have all been shown to promote lung cancer progression, while SAMHD1, HRAS, and NQO1 serve as tumor suppressor genes." (PMID 28498804, 2017). "Another previous study exploring the interaction partners of ARHGEF39 identified RAC1, but not RHOA (or CDC42) in a pulldown assay from lung cancer cells overexpressing ARHGEF39." (PMID 35959104, 2022). "It was found that knockdown of CDC42 or N-WASP significantly decreased the percentage of invadopodia cells induced by PDBu, which was consistent with the results of the overexpression of miR-182 in lung cancer cells." (PMID 29986736, 2018).
lung carcinoma (continued). "Suppression of CNTN1 expression abolished the ability of lung cancer cells to invade and metastasize by activating RhoA, but not Cdc42 or Rac1, suggesting that CNTN1 is a key regulator of invasion and metastasis in lung adenocarcinoma." (PMID 22580838, 2012). "Among others, these include CASP9 and CDC42 (1p36), which have already been studied in neuroblastoma; CACNA2D3 (3p21-p22), which was recently proposed as a tumor suppressor gene in lung cancer; IGSF4 (11q23), which is a known tumor suppressor gene in several cancers; and DLK1 (14q)." (PMID 16989664, 2006). "Further, Cdc42 and p-FAK (phosphorylated at Tyr397) were not affected by the treatment in both lung cancer cells." (PMID 33530617, 2021).
colorectal cancer (48 papers, 2012 to 2026). A primary or metastatic malignant neoplasm that affects the colon or rectum. "Increased Cdc42 levels have been associated with colorectal cancer progression by promoting colorectal cancer cell migration and invasion and regulating the putative tumor suppressor gene ID4." (PMID 37365285, 2023). "Recently, a study has shown that aberrant expression of CDC42 in colorectal cancer can cause the migration, invasion, and metastasis through activation of the VEGF/NRP1 axis and is closely related to the prognosis of the patients." (PMID 34291059, 2021). "For example, Cdc42 overexpression is found in colorectal cancer, and is associated with the potential tumor suppressor gene ID4." (PMID 32392742, 2020). "Cdc42 activity has also been implicated in the proliferation and invasion of colorectal cancer cells involving downstream PAK signaling, suggesting that Cdc42 may be a useful target for therapeutic intervention in addition to Rac1 inhibition." (PMID 24040362, 2013). "Background and Objectives: Aberrant activation or overexpression of cell division cycle 42 (Cdc42) has been demonstrated in various tumors; however, its prognostic relevance in colorectal cancer (CRC) remains insufficiently defined." (PMID 42194810, 2026). "Materials and Methods: Cdc42 expression was assessed by immunohistochemistry in patients with colorectal cancer who underwent colectomy for curative or palliative purposes between January 2009 and January 2019." (PMID 42194810, 2026). "The specific inhibitor of Cdc42, CASIN, decreased the oncogenicity of four Cdc42-overexpressing colorectal cancer cell lines (LIM1863, Caco2, LIM1899, and LIM2551) in vitro." (PMID 39458630, 2024). "A distinct scaffolding function was observed in CEMIP, mediating GRAF1 and MIB1 coordination, thereby instigating metastatic events in colorectal cancer through CDC42/MAPK pathway activation." (PMID 39624211, 2024). "Our results further emphasize the need for more investigation into the function of Cdc42 in the progression of colorectal cancer and the mechanisms governing the control of Cdc42 and oncogenic signaling pathways." (PMID 39458630, 2024). "In the context of colorectal cancer, the genes CDC42, TAGLN, and GSN have gained increasing recognition due to their significant involvement in key processes related to cancer progression and metastasis." (PMID 37365287, 2023). "The present study aimed to investigate the elusive expression pattern of CDC42, TAGLN, and GSN genes in patients with high and low-risk polyp samples, and also colorectal cancer patients and their adjacent normal tissues." (PMID 37365287, 2023). "Lastly, the study suggests the potential utility of the CDC42, TAGLN, and GSN genes as diagnostic or prognostic markers for colorectal cancer." (PMID 37365287, 2023). "Cdc42 induces actin polymerization at the front edge of the lamellar lipid membrane to promote the metastasis of colorectal cancer cells." (PMID 35154449, 2022). "We also provide mechanistic insight into its translational activation ability on Cdc42 and RhoA, thus promoting pseudopodia formation and cytoskeleton reorganization of colorectal cancer cells." (PMID 35300416, 2022). "In colorectal cancer, Cdc42 is involved in cancer cell proliferation through the PAK-mediated tight junction and AJC." (PMID 35154449, 2022). "Noteworthy, although the overexpression of Cdc42 in colorectal cancer and its clinical relevance have been studied to some extent, the role of CDC42EP3 in colorectal cancer has not been reported, which attracted our attention." (PMID 33726765, 2021). "In general, the movement of intestinal epithelial cell depends on direction, lamellipodial protrusion, adhesion formation and cell polarization; thus, it was also proven that CDC42 modulates directly colorectal cancer cell invasion in vitro." (PMID 33406731, 2021).
colorectal cancer (continued). "Quantitative PCR showed significantly elevated expression of canonical CDC42 (V1) in human colorectal cancer tissues, compared with adjacent normal tissues (N = 41 pairs of samples), consistent with a previous report." (PMID 32686657, 2020). "miR-137 likely works through the suppression of either the Cdc42-PAK1-MLC or ERK signaling pathway and the proliferation/invasion of colorectal cancer cells by mimicking the effects of Cdc42 knockdown." (PMID 32722415, 2020). "Overexpression of Cdc42 was found in colorectal cells, and Cdc42 activation is thought to be one of the keys to the malignant progression of human colorectal cancer with increased cellular invasiveness." (PMID 29596304, 2018). "We have previously reported that CDC42 is overexpressed in colorectal cancer and silenced the TSG ID4 through an epigenetic mechanism." (PMID 28460460, 2017). "Collectively, our findings indicate that PTEN C2 coordinates β-Arrestin1-ARHGAP21 and Cdc42-dependent multicellular morphogenesis in a 3D colorectal cancer model system." (PMID 28749339, 2017). "Specifically, CDC42 has been shown to induce cellular transformation, invasion, and metastasis in several tissue types including melanoma, breast cancer, and colorectal cancer." (PMID 28282856, 2017). "To further validate this CDC42-driven transcriptional signature in the context of colorectal cancer, we used RNAseq data for a total of 628 CRC patients from The Cancer Genome Atlas (TCGA) Rectum Adenocarcinoma (READ) and Colon Adenocarcinoma (COAD) datasets." (PMID 28460460, 2017). "In the same way, human colorectal cancer with higher levels of Cdc42 activity was especially sensitive to Cdc42 blockade." (PMID 26964533, 2016). "Hsa-miR-330-3p has been demonstrated to regulate cellular motility by down regulating SP1 in prostate cancer cells, and proliferation by reducing CDC42 levels in colorectal cancer." (PMID 26967895, 2016). "In colorectal cancer miR-330-3p is also reported as a tumour suppressor by repressing the translation of CDC42 and negatively regulating proliferation." (PMID 26221725, 2015). "This is supported by a report suggesting that active Cdc42 can enhance colorectal cancer cell migration and invasion." (PMID 24279335, 2013). "In summary, the present study describes a novel small molecule inhibitor which can be used to effectively inhibit the Rho GTPase Cdc42 in the treatment of KRAS mutant colorectal cancers." (PMID 24279335, 2013). "In this study, we first compared the invasiveness of a collection of colorectal cancer cell lines with their RhoA, Rac1 and Cdc42 activities." (PMID 23144867, 2012). "A marked decrease in active Cdc42 and Rac1 was observed in the most invasive colorectal cancer cell lines." (PMID 23144867, 2012). "Cdc42 activation has been related to several malignancies, including colorectal cancer." (PMID 37365285, 2023). "The research reported that miR-137 may directly target CDC42, inducing G1 cell cycle arrest and inhibiting the proliferation and invasion activities of colorectal cancer cells." (PMID 33152231, 2021). "These indicated that NDRG1 might reduce the activity of CDC42, to regulate actin cytoskeletal dynamics in colorectal cancer cells." (PMID 33994856, 2021). "Here, we found that compared to apical expression of Cdc42, which indicated that basal expression of Cdc42 occurred at the migrating cell front, glandular basal expression of Cdc42 (cell division cycle 42) in tissues indicated poorer prognoses for colorectal cancer (CRC) patients." (PMID 32139668, 2020). "CDC42 is an oncogenic Rho GTPase overexpressed in colorectal cancer (CRC)." (PMID 28460460, 2017). "Furthermore, the genetic knockout of CDC42 results in cell cycle arrest and apoptosis in colorectal cancer." (PMID 28282856, 2017).